ENO1 (enolase 1)
Diseases named in the same sentence as ENO1 in open-access papers (continued):
Sharing a sentence is not in itself a finding about the gene and the disease.
breast carcinoma (continued). "Elevated titers of anti-ENO-1 antibodies in sera from breast cancer patients were described as well." (PMID 25407528, 2014). "Elevated expression of ENO1 has been observed in many types of tumors and surface expression of ENO1 has been reported in lung, pancreatic and breast cancer cells." (PMID 23894455, 2013). "Upregulation of ENO1 gene has been observed in several highly tumorigenic or metastatic cell lines and enzymatic activities in breast cancer concluded a role of ENO1 in tumor progression." (PMID 22014164, 2011). "The present study examined the expression of ENO1 and assessed its significance in canine mammary carcinoma." (PMID 22014164, 2011). "In this study, we investigated the expression and clinical relevance of ENO1 in canine mammary carcinoma." (PMID 22014164, 2011). "More recently, higher ENO1 expression was detected in ER+ breast cancer patients compared to ER- patients." (PMID 22014164, 2011). "While it was seen in the more aggressive subtype of breast cancer, our study showed ENO1 elevation in HER2-positive tumors seemed to indicate a better tumor response to chemotherapy." (PMID 22110952, 2011). "Increased expression of ENO1 has recently been reported in estrogen (ER)-positive human breast cancer patients." (PMID 22014164, 2011). "Immunohistochemical analyses revealed that mammary carcinomas have higher expression of ENO1 as compared to benign tumors." (PMID 22014164, 2011). "Immunohistochemical staining was employed to investigate the expression of ENO1 in 82 cases of canine mammary tumor (32 benign tumors and 50 carcinomas)." (PMID 22014164, 2011). "The glycolytic enzyme enolase-1 as well as HSP27, two additional proteins identified in the 2D-gel experiments, are associated with high metastatic activity in breast cancer cells." (PMID 17211471, 2007). "(2025) identified ENO1 as a novel therapeutic target capable of enhancing antitumor immunity and improving clinical outcomes in breast cancer patients, indicating that ENO1 may be a promising therapeutic target." (PMID 41179678, 2025). "Notably, upregulated expression of ENO1 was verified to participate in multiple drug resistance in methotrexate resistant human breast cancer cells." (PMID 40612109, 2025). "In breast cancer, ENO1’s role can be context-dependent: in early-stage breast cancer, higher ENO1 expression correlates with better survival and increased anti-tumor immune infiltration, while in advanced disease, it is associated with progression and immune evasion." (PMID 41373732, 2025). "Therefore, a relationship can be inferred between the intensity of ENO1 immunohistochemical staining and the clinical outcomes of breast cancer patients." (PMID 41179678, 2025). "Studies are required to determine the contributions of ENO1 to the progression of breast cancer." (PMID 40214422, 2025). "ENO1 gene expression is increased in various cancer types, including breast cancer." (PMID 39239354, 2024). "Moreover, ENO1 promotes the occurrence of various cancers, including breast cancer, through the PI3K/AKT pathway, and the PI3K/AKT pathway is also inhibited in liver cancer cells after inhibiting ENO1." (PMID 39576845, 2024). "In the realm of breast cancer, enolase 1 (ENO1) stands as an illustrative example." (PMID 38250812, 2023). "Third, the hormonal status of breast cancer may affect the significance of the ENO1/MSN-Mtdh regulatory axis in response to lymphocyte-derived iTSC CM." (PMID 36923539, 2023). "Proteomics profiling revealed high enolase-1 (ENO-1) expression in ER+ breast carcinomas." (PMID 35433453, 2022). "In a study of breast cancer, a xenograft model was established by injecting breast cancer cells with small interfering RNA (siRNA) ENO1 into nude mice; reduced angiogenesis in the tumor tissue was observed with declined tumor growth and diminished tumor volume and weight." (PMID 35434271, 2022).
breast carcinoma (continued). "In breast cancer, elevated expression of ENO1 has been reported to be closely related to tamoxifen resistance and adriamycin resistance, and silencing of ENO expression significantly increases the cytotoxicity of 100 nM tamoxifen in tamoxifen-resistant breast cancer cells." (PMID 36059650, 2022). "Furthermore, ENO1 promotes the proliferation and metastasis of breast cancer cells through the PI3K/AKT pathway, and in turn is upregulated by HIF1α." (PMID 35443744, 2022). "Moreover, analysis of 244 samples of breast cancer tissue revealed strong expression of ENO-1 in ER breast cancer, showing that it is also an important marker for BC." (PMID 36059650, 2022). "A previous study indicated that overexpression of ENO1 could enhance the resistance toward tamoxifen, whereas decreased expression of ENO1 could exhibit the opposite result in human breast cancer cells." (PMID 36620599, 2022). "In breast cancer, ENO1 overexpression correlates with larger tumor size and poor nodal status." (PMID 35434271, 2022). "Furthermore, the daily administration of Eno1 proteins at 1 μg/kg significantly reduced the growth of mammary tumors of C57BL/6 female mice in 2 weeks." (PMID 35547745, 2022). "Moreover, UBE3A reportedly causes reduced expression of the oncogenic proteins AIB1 (amplified in breast cancer 1) and Enolase1 (ENO1) in breast cancer cells." (PMID 34421347, 2021). "Previous studies found that the upregulation of ENO1 was positively correlated with progression and poor prognosis in breast cancer, prostate cancer, thyroid carcinoma, hepatocellular carcinoma, cholangiocarcinoma, neuroblastoma, neuroendocrine tumors, lung cancer, and pancreatic cancer." (PMID 33643901, 2020). "We focused on the clinical relevance of ENO1 and MMPs (MMP-2 and MMP-9) overexpression in breast cancer tissues: The association between the higher ENO1, MMP-2 and MMP-9 expression with a worse prognosis suggest that the elevated ENO1 and MMPs expression are promising biomarkers for breast cancer." (PMID 31416219, 2019). "Interestingly, high level of ENO1 protein with low ENO1 mRNA level was also detected in methotrexate-resistant breast cancer cells." (PMID 28548950, 2017). "Hence, the expression of enolase-1 in our study validates its role in breast cancer cell energy requirements." (PMID 27110560, 2016). "Increased expression of ENO-1 was also found in breast cancer tissue." (PMID 25407528, 2014). "This suggests that targeting ENO-1 in breast cancer cells may be a novel therapeutic approach to overcome 4-OHT resistance." (PMID 25407528, 2014). "Up-regulation of α-enolase expression has been extensively reported for several types of cancer, including hepatocellular carcinoma, thyroid oncocytoma, lung and breast cancers among many others, and ENO1 gene expression is increased in 18 of 24 cancers classes analyzed." (PMID 25171719, 2014). "Our findings suggest that overexpression of ENO1 may be used as a prognostic marker for poor outcome in canine mammary carcinoma." (PMID 22014164, 2011). "Among them apolipoprotein A-I and D, enolase 1, tumor rejection antigen (gp96) 1, transgelin 2, cofilin 1, profilin, heat shock proteins 70, and annexins 5 were found to be present in significant quantity in both types of breast cancer." (PMID 22110952, 2011). "In addition, previous studies have confirmed that ENO1 not only promotes cell survival by regulating glycolysis in breast cancer but also may interact with HSP70 to protect hepatocytes from heat stress." (PMID 40941354, 2025). "Silencing of ENO1 gene in a breast cancer cell line reduced the proliferative capacity of the cells, indicating that ENO1 could be a potential molecular prognostic marker or therapeutic target in breast cancer." (PMID 39239354, 2024). "Furthermore, downregulation of enolase-1 improves the cellular sensitivity to the radiation therapy and it might be the target for drug development for breast cancer." (PMID 27110560, 2016).
breast carcinoma (continued). "However, the serum level of anti-ENO1 Ab in late-stage patients with lung or breast cancer has been found to be lower as compared to those in healthy donors, and the level of anti-ENO1 Ab in advanced stage NSCLC patients has been shown to be lower than that of early-stage patients." (PMID 26551021, 2015). "The finding of ENO1 overexpression in the neoplastic tissue of canine mammary carcinoma and its possible role in the prognosis of this disease is clinically relevant, as ENO1 expression could be widely determined on routinely processed, paraffin-embedded tissues." (PMID 22014164, 2011). "Moreover, agents with ENO1 attenuation activity might provide an effective strategy for the treatment of breast cancer for both dogs and human and merit further investigation." (PMID 22014164, 2011). "The stabilization of WTAP further promotes the m6A methylation of enolase 1 (ENO1), influencing the glycolytic activity of breast cancer cells and thereby promoting tumor growth in vivo; this effect is abolished following WTAP silencing." (PMID 40387965, 2025). "Five potential AAb biomarkers (HSPA4, ENO1, PRDX6, PRPF19, MMP14) predictive of breast cancer were identified through verification and validation cohorts." (PMID 40766308, 2025). "Anti-HSPA4, anti-PRPF19, anti-ENO1, anti-PRDX6, and anti-MMP14 autoantibodies showed significant increases in breast cancer patients." (PMID 40766308, 2025). "In the verification cohort, IgG autoantibodies against HSPA4, ENO1, PRDX6, PRPF19 and MMP14 were significantly increased in breast cancer patients with areas under the curve (AUCs) of 0.90, 0.89, 0.82, 0.78 and 0.77, respectively." (PMID 40766308, 2025). "Similar to NEAT1 in breast cancer, the c-Myc-responsive lncRNA glycoLINC (gLINC) promotes glycolysis by acting as a scaffold for glycolytic enzymes, including PGK1, ENO1, PKM2, and LDHA, with indirect binding to PGAM1." (PMID 40804479, 2025). "Elevated levels of NEAT1 in breast cancer enhance glycolysis by scaffolding key glycolytic enzymes, including PGK1, PGAM1, and ENO1, concurrently within the same cellular context, thereby promoting breast cancer progression and metabolism." (PMID 40711448, 2025). "We validated these five autoantibodies (HSPA4, ENO1, PRDX6, PRPF19, and MMP14) in an independent cohort of 33 breast cancer patients and 45 healthy controls." (PMID 40766308, 2025). "The Mann-Whitney U test showed that five AAbs (HSPA4, PRPF19, ENO1, PRDX6, and MMP14) were significantly higher in the breast cancer group than in the control group." (PMID 40766308, 2025). "Recent studies have found that ENO1 participates in the EMT-regulating process in lung cancer, gastric cancer, and breast cancer." (PMID 36614179, 2023). "Several known proteins (including HSP90AB1, HSPB1, LDHA, ENO1, PGK1, KRT18, and AKR1C2) and pathways were observed between model breast cancer cell lines related to hormone response, cell metabolism, and cell morphology." (PMID 36937585, 2023). "Similar to our study, the authors found upregulation of the hypoxia-related genes ENO1, FOXO3, VEGF, LDH, and NPRG1 in recurrent patients with high grade breast cancer tumors." (PMID 33804802, 2021). "The another study also identify that the decreasing of serum ENO1 antibody is a marker in late stage of NSCLC, SCLC and breast cancers." (PMID 34671213, 2021). "Eno1 and Ubc inhibited the scratch-based migration of EO771 breast cancer, as well as the proliferation and invasion of TRAMP prostate and PANC-1 pancreatic cancer cells." (PMID 34373756, 2021). "According to reports, patients with tumors with high expression of ENO1 have a poor prognosis, including NSCLC, breast cancer, glioma, bladder cancer, pancreatic cancer, liver cancer, and gastric cancer." (PMID 34504528, 2021). "ELISA and Western blotting confirmed that the levels of Eno1 and Ubc were elevated in EO771 mammary tumor cell-derived iTS CM." (PMID 34373756, 2021).
breast carcinoma (continued). "We observed that the application of β-catenin-overexpressing iTS CM, Eno1, and Ubc significantly reduced the level of PD-L1 in EO771 mammary tumor cells as well as TRAMP prostate tumor cells." (PMID 34373756, 2021). "Like ERRα activity, the mRNA levels of ERRα target genes, KLK3, ENO1 or TAPBPL, were also significantly elevated in GREM1-overexpressing breast cancer cells." (PMID 32572171, 2020). "Here, we provide new evidences about the clinical relevance of ENO1 and MMPs (MMP-2 and MMP-9) overexpression in breast cancer tissues." (PMID 31416219, 2019). "Increased enolase 1 (ENO1) mRNA m6A modification facilitates its binding to the m6A reader YTHDF1 and results in enhanced translation, leading to aerobic glycolysis in human lung adenocarcinoma and breast cancer." (PMID 37192910, 2023). "Finally, KM Plotter analysis of the hub genes showed that the high expression of ADM, ENO1, PLOD1, and CEBPB was significantly correlated with a shorter OS and poor prognosis in patients with breast cancer." (PMID 37391802, 2023). "The correlation between ENO1 and MDR in breast cancer may be regulated by activating the ERK1/2 pathway, and it is likely to be regulated by c-Myc." (PMID 36059650, 2022). "Additionally, ENO1 and LDHA were reported to promote the EMT and stemness in lung and breast cancer cells, suggesting that upregulation of glycolytic genes by YBX1 plays a crucial role in promoting tumor aggressiveness." (PMID 34440660, 2021). "As occurs in breast cancer and NSCLC 15, 16, 43, ENO1 surface and nuclear forms may be involved in cancer invasion and metastasis, as well as in transcriptional repression, apparently inhibiting cell growth and accelerating apoptosis and necrosis." (PMID 33628097, 2021). "Furthermore, siRNA-mediated silencing of Eno1 and Ubc promoted the proliferation and migration of EO771 mammary tumor cells and blocked the inhibitory effects of β-catenin-overexpressing CM on mammary, prostate, and pancreatic tumor cells." (PMID 34373756, 2021). "ENO1 also involves in cell adhesion-mediated resistance in non-Hodgkin lymphoma and tamoxifen resistance in breast cancer." (PMID 33643901, 2020). "The expression levels of ENO1 (48 kDa) was evaluated by western blot in a subset of 24 breast cancer tissues and their paired non-tumoral adjacent tissues." (PMID 31416219, 2019). "O-GlcNAcylation of enolase 1 (ENO1) was also reported in a breast cancer cell line, T47D, but the glycosylation sites have not yet been identified." (PMID 25426101, 2014). "Overexpression of ENO1 (as defined by a Quick score of 12 or greater) was only identified in 18% (9/50) of dogs with mammary carcinoma and none in the benign tumors." (PMID 22014164, 2011). "Enolase-1 has been correlated to a negative prognosis in late-stage breast cancer patients." (PMID 41149583, 2025). "ENO1 was not considered a significant predictor of prognosis in breast cancer patients." (PMID 41179678, 2025). "Although there has been a single published study on Enolase 1 in canine mammary tumors that used the immunohistochemical technique, it did not focus on the various prognostic regulations that this protein can influence depending on the labeling site, as ours did." (PMID 40005870, 2025). "Moreover, ENO1 overexpression occurred preferentially in the tumor cells and not the adjacent non-tumor cells in mammary carcinoma (P = 0.011)." (PMID 22014164, 2011). "Our results showed that ENO1, MMP-2 and MMP-9 are overexpressed in breast cancer tissues compared to the non-tumoral adjacent one, and how their higher expression level is associated with a worse prognosis." (PMID 31416219, 2019).
breast carcinoma (continued). "Similarly, in MCF7 breast cancer cells SLC2A1, HK2, and PFKFB3 but not ENO1 or LDHA were strongly induced by hypoxia." (PMID 23866118, 2013). "Using transcriptome sequencing data of the CSC subpopulation in SUM149 human breast cancer cell line from GSE132083, we compared the glycolytic gene expression profiles between the CSC group and non-CSC group, and found that SLC2A1, HK2, ALDOA, ENO1, LDHA and PDK1 were upregulated in the CSC group." (PMID 34052833, 2021).